TCF7 (transcription factor 7)
Diseases named in the same sentence as TCF7 in open-access papers (continued):
Sharing a sentence is not in itself a finding about the gene and the disease.
metastatic melanoma (2 papers, 2020 to 2025). A melanoma that has spread from its primary site to another anatomic site. "A previous single-cell metastatic melanoma study established an association between TCF7 + CD8 T cells and ICI response." (PMID 40890106, 2025). "Moreover, regardless of the overall T cell infiltration, an increased presence of memory-like CD8+TCF7+ T cells (as opposed to generally exhausted CD8+TCF7− T cells) is associated with an increased response to PD-1 blockade in patients with metastatic melanoma." (PMID 32457745, 2020).
Oral Squamous Cell Carcinoma (2 papers, 2022 to 2024). "Ping Zhou recently reported that identification of E2F transcription factor 7 as a novel potential biomarker for oral squamous cell carcinoma." (PMID 38271139, 2024).
osteosarcoma (2 papers, 2021). A usually aggressive malignant bone-forming mesenchymal neoplasm, predominantly affecting adolescents and young adults. "Upregulation of miR-192 suppresses the progress of osteosarcoma through targeting USP1, TCF7, and XIAP." (PMID 33614788, 2021).
pancreatic ductal adenocarcinoma (2 papers, 2022 to 2024). An infiltrating adenocarcinoma that arises from the epithelial cells of the pancreas. "In human pancreatic ductal adenocarcinoma, USP21 activated the Wnt pathway to promote the stemness of cancer cells by acting as a deubiquitinase of TCF7." (PMID 38906857, 2024). "Transcriptome profile showed elevated TCF7, CTNNB1, and JUN expression in pancreatic ductal adenocarcinoma." (PMID 36457029, 2022).
rheumatoid arthritis (2 papers, 2017 to 2020). A chronic, systemic autoimmune disorder characterized by inflammation in the synovial membranes and articular surfaces. "The top 50 DEG include genes with variants previously associated with SS (CXCR5), SLE (CXCR5, PPP2CA, and TCF7), and rheumatoid arthritis (FCRL3)." (PMID 32650575, 2020).
Sepsis (2 papers, 2012 to 2025). Sepsis is defined as life-threatening organ dysfunction caused by a dysregulated host response to infection. "Transcriptional regulators like PLAGL2, EBF1, TCF7, KLF10 and SBNO2, previously not described in sepsis, are differentially expressed at early and late time points." (PMID 23009705, 2012).
type 2 diabetes (2 papers, 2018 to 2019). "Wnt signalling is also linked with a risk of type 2 diabetes because it can bind to the co-activator of β-catenin TCF7/L2, and the Wnt/β-catenin pathway is responsive to glucose." (PMID 31540087, 2019). "Variants of the TCF7/2 gene are linked to increased susceptibility for type 2 diabetes, while a SNP in the human WNT10b gene has been associated with early-onset familial obesity." (PMID 29514067, 2018).
acute myeloid leukemia (1 paper, 2021). Acute myeloid leukemia (AML) is a group of neoplasms arising from precursor cells committed to the myeloid cell-line differentiation. "This inhibitor suppressed the expression of WNT target genes (CCND1, LEF1 and TCF7) in mantle cell lymphoma (MCL) and strongly impaired cell proliferation and induced apoptosis in vitro in MCL and in acute myeloid leukemia (AML) cell lines." (PMID 34771683, 2021).
adenovirus infection (1 paper, 2023). "Moreover, the presence of SFRP5 and TCF7 in the tan module suggests that the WNT signaling pathway may be involved in adenovirus infection." (PMID 37017816, 2023).
anaplastic large cell lymphoma (1 paper, 2023). Anaplastic large cell lymphoma (ALCL) is a rare and aggressive peripheral T-cell non-Hodgkin lymphoma, belonging to the group of CD30-positive lymphoproliferative disorders, which affects lymph nodes and extranodal sites. "In addition, BATF3 drives Th17-skewing phenotype in anaplastic large cell lymphoma (ALCL), and TCF7 confers progenitor exhausted T cell state." (PMID 37790936, 2023).
Angelman syndrome (1 paper, 2019). A neurogenetic disorder characterized by severe intellectual deficit and distinct facial dysmorphic features. "Previous studies have demonstrated that the invasion and migration ability of CRC cells can be inhibited by the down-regulation of lncRNA Angelman syndrome chromosome region (ANCR), HOTAIR, and transcription factor 7 (TCF7)." (PMID 31693738, 2019).
angioleiomyoma (1 paper, 2018). A benign, slow-growing neoplasm that arises from the dermis or subcutaneous tissue. "Only six genes show significant differences between the angioleiomyoma types (ISL1, NCSTN, TCF7, WNT10A, WNT11, WNT7A) but their relative expression levels were very low, which indicates no biological relevance (< 0.4 compared to standardized reference gene index)." (PMID 29881541, 2018).
Blindness (1 paper, 2018). Blindness is the condition of lacking visual perception defined as a profound reduction in visual perception. "For example, temporal headache at T1 as well as bilateral blindness showed significant association with CD8 expression of TCF7 (TH: beta = − 0.151, adj." (PMID 30037347, 2018). "For example, temporal headache at T1 as well as bilateral blindness showed significant association with CD8 expression of TCF7, which is important for adaptive T lymphocyte and innate lymphoid cell regulation." (PMID 30037347, 2018).
chordoma (1 paper, 2023). Chordomas are rare malignant tumors arising from embryonic remnants of the notochord in axial skeleton. "Additionally, CD4 T‐cell clusters had widespread overexpression of naïve markers (CCR7, SELL, LEF1 and TCF7), suggesting that CD4 T cells were in a naïve state in chordoma." (PMID 37784253, 2023).
chronic obstructive pulmonary disease (1 paper, 2017). A chronic and progressive lung disorder characterized by the loss of elasticity of the bronchial tree and the air sacs, destruction of the air sacs wall, thickening of the bronchial wall, and mucous accumulation in the bronchial tree. "In another study, gene expression profiling of PBMCs obtained from smokers exhibited a signature of chronic obstructive pulmonary disease (COPD) and emphysema characterized by multiple differentially regulation of genes FOXP1, TCF7, and ASAH1 involved in sphingolipid (ceramide) metabolism." (PMID 29376056, 2017).
colon adenocarcinoma (1 paper, 2024). "The results showed that the SNV frequencies of TCF4, TCF3, and TCF7 were highest in UCEC (42% for TCF4, 14% for TCF3 and TCF7), followed by skin cutaneous melanoma (SKCM) (38% for TCF4, 10% for TCF3, and 4% for TCF7) and colon adenocarcinoma (COAD) (13% for TCF4, 10% for TCF3, and 8% for TCF7)." (PMID 39205642, 2024).
cystic fibrosis (1 paper, 2021). Autosomal recessive disorder caused by pathogenic variants in the CFTR gene (cystic fibrosis transmembrane conductance regulator), which encodes a chloride and bicarbonate channel expressed in epithelial cells, and follow the diagnosis criteria. "These included the chloride channel that is most frequently mutated in patients with cystic fibrosis (CFTR) and the negative regulator of Wnt signaling TCF7." (PMID 33892786, 2021).
emphysema (1 paper, 2014). "Downregulation of TCF7 was found in PBMCs of patients with COPD and current smoking and was correlated with some clinical phenotypes, such as emphysema, gas trapping and distance walked." (PMID 25407108, 2014).
Granuloma (1 paper, 2022). A compact, organized collection of mature mononuclear phagocytes, which may be but is not necessarily accompanied by accessory features such as necrosis. "The most abundant subcluster (8.3% of granuloma cells, q = 0.074, Dirichlet p = 0.00049) exhibited elevated expression of markers of naive and memory T cells (TCF7, CCR7, IL7R, and TXNIP) and activation or memory state (CD69 and ITGB1)." (PMID 35483355, 2022).
hepatoblastoma (1 paper, 2021). Hepatoblastoma (HB) is a malignant hepatic tumor and is the most common pediatric liver cancer. "TCF7 has been reported to be co-expressed with NBR2, and NBR2 deficiency leads to decreased TCF7 expression in hepatoblastoma cells, along with the down-regulation of the TCF7 protein that is involved in cell cycle progression, glucose entrapment, and epithelial-mesenchymal transition (EMT)." (PMID 34926299, 2021). "TCF7 has been defined as the target molecule of miR-22 and NBR2, which is localized in both the cytoplasm and nucleus, aggravates hepatoblastoma cell malignancy by sponging miR-22 under conditions of glucose starvation, thereby counteracting miR-22-induced TCF7 repression." (PMID 34926299, 2021).
intestinal polyposis (1 paper, 2021). "fl-Tcf4 and dnTcf7 transcripts are the predominant Tcf/Lef1 family isoforms expressed in the intestine, which explains the opposite intestinal phenotypes in mice deleted of Tcf7l2 (lack of cycling stem cells) versus Tcf7 (intestinal polyposis)." (PMID 34788095, 2021).
latent infection (1 paper, 2022). "This was in contrast to Tcf7+ cells from latent infection, which maintained relatively higher levels of Gzmm, Ifngr1, and Ccl5." (PMID 35185882, 2022). "This led us to induce latent infection using an identical strain and dose of MCMV-ie2-gp33 as performed in our recent work that had elucidated a population of Tcf7+ T cells that sustain the inflationary population during MCMV infection." (PMID 35185882, 2022).
leukoplakia (1 paper, 2021). A white patch or plaque on a mucous membrane that cannot be characterized clinically or pathologically as any other disease. "Also notable was the overexpression of TCF7 among proliferative leukoplakia (log2 fold change 1.18; Padj = 0.001)." (PMID 36860910, 2021). "Binary logistic regression modeling suggested greater log2 expression among CYLD (OR = 9.01) and TCF7 (OR = 6.29) predicted risk of progression to cancer regardless of localized leukoplakia or PL phenotype (both P = 0.01 or less)." (PMID 36860910, 2021). "In addition, CYLD, CARD11, TCF7, CCR7, KLRB1, CD28, and ICOS were other significantly highly expressed genes among the proliferative leukoplakia subgroup (log2 fold changes, 0.65–3.51; all Padj = 0.001)." (PMID 36860910, 2021).
lymph node metastasis (1 paper, 2022). "TCF7+ T cells were associated with T stage, lymph node metastasis and TNM stage, with statistically significant differences (p<0.05), but not with sex, age, tobacco, alcohol, histological grade, or CD3 density (p> 0.05)." (PMID 35345446, 2022).
meningioma (1 paper, 2025). A generally slow growing tumor attached to the dura mater. "Despite this, there was a noted increase in FOXP3 expression in meningioma compared to the control tissues and VS tumours, and genes associated with T cell exhaustion in VS (TOX and TCF7)." (PMID 41437121, 2025).
metastatic tumor (1 paper, 2015). "Furthermore, the mean expression analysis of the clinical prostate database showed reduced miR-34a and increased TCF7 expression in metastatic tumor samples compared to primary stage tumors and normal prostate tissues." (PMID 25436980, 2015).
multiple sclerosis (1 paper, 2015). A progressive autoimmune disorder affecting the central nervous system resulting in demyelination. "Furthermore, T cells from multiple sclerosis patients exhibit lower TCF7 expression than those from healthy individuals, and FTY720 treatment upregulates TCF7 expression in T cells from both healthy controls and patients." (PMID 26714756, 2015). "To determine whether this increase in TCF7 expression was specifically brought about by FTY720, we activated T cells in the presence of other approved drugs for multiple sclerosis treatment, namely interferon beta and natalizumab." (PMID 26714756, 2015).
mycosis fungoides (1 paper, 2021). Classical mycosis fungoides is the most common type of mycosis fungoides (MF), a form of cutaneous T-cell lymphoma, and is characterized by slow progression from patches to more infiltrated plaques and eventually to tumors. "The TCF7 gene upregulation was described in some of the uncommon human mycosis fungoides (MF) cases as exhibiting an aggressive behavior." (PMID 33504055, 2021).
myeloma (1 paper, 2023). "LncRNA TCF7 promotes cell proliferation and reduces cell apoptosis through downregulating miR‐200c in myeloma cells." (PMID 36057947, 2023).
non-small cell lung carcinoma (1 paper, 2026). A group of at least three distinct histological types of lung cancer, including non-small cell squamous cell carcinoma, adenocarcinoma, and large cell carcinoma. "In anti-PD-1 responding non-small cell lung cancer patients, Mettl8 and the stemness factor TCF7 were downregulated." (PMID 41891923, 2026).
ovarian tumors (1 paper, 2025). "Developing 2 Uni-Vect systems to combine a constitutive HER2-targeting CAR with NFAT-inducible FOXO1 or TCF7, researchers validated improved proliferation and persistence of CAR-T cells in ovarian tumors." (PMID 40693464, 2025).
parasitic diseases (1 paper, 2023). "From this, we identified 26 common DEGs downregulated in Tr1 cells from both parasitic diseases, including Ccr7, Tcf7, and Bcl6, as well as 29 upregulated DEGs, including Il10, Havcr2, Prdm1, Ccr2, Ccr5, Maf, and Lag3." (PMID 37917177, 2023).
periodontitis (1 paper, 2019). An acute or chronic inflammatory process that affects the tissues that surround and support the teeth. "However, in Dkk-1 conditional knock-out mice with periodontitis, TCF-7 expression remained at control level." (PMID 31921182, 2019). "Periodontitis tended to reduce the expression of LEF-1 and drastically reduced TCF-7 expression in wildtype littermates." (PMID 31921182, 2019).
peripheral T-cell lymphomas (1 paper, 2021). "Additionally, the protein expression of TCF7 was shown in human peripheral T-cell lymphomas expressing markers of Th1 activation." (PMID 33504055, 2021).
pulmonary diseases (1 paper, 2025). "FAM13A, ERBB2, and TCF7 are associated with lung function and various pulmonary diseases in mammals." (PMID 41190333, 2025).
pulmonary fibrosis (1 paper, 2015). Chronic progressive interstitial lung disorder characterized by the replacement of the lung tissue by connective tissue, leading to progressive dyspnea, respiratory failure, or right heart failure. "TCF7 also plays an important role in tissue repair and remodeling after acute lung injury or in the development of pulmonary fibrosis." (PMID 26289446, 2015). "Overexpression of Wnt genes (WNT2 and −5a), the receptors (FZD7 and −10), WNT regulators (sFRP1 and −2), and Wnt target genes (MMP7) was reported in lung fibrosis, while the expression of TCF7 did not increase." (PMID 26289446, 2015).
relapsing-remitting multiple sclerosis (1 paper, 2015). The most common clinical variant of multiple sclerosis, characterized by recurrent acute exacerbations of neurologic dysfunction followed by partial or complete recovery. "We found significantly decreased TCF7 expression in T cells from relapsing-remitting multiple sclerosis patients compared with those from healthy individuals and the treatment with FTY720 increased TCF-1 expression in both groups." (PMID 26714756, 2015).
respiratory failure (1 paper, 2014). The significant impairment of gas exchange within the lungs resulting in hypoxia, hypercarbia, or both, to the extent that organ tissue perfusion is severely compromised. "Indeed TCF-7 was down regulated in COPD, but also in CF and PAH, evidencing a modulation of TCF-7 in response to respiratory failure, whatever its cause." (PMID 25329529, 2014).
sarcoidosis (1 paper, 2025). Sarcoidosis is a multisystemic disorder of unknown cause characterized by the formation of immune granulomas in involved organs. "Additionally, CD4+ T cells from sarcoidosis patients exhibited increased PRDM1 and GATA3 expression, while naive markers SELL, TCF7 and LEF1 were reduced in sarcoidosis and active TU compared with healthy donors." (PMID 40469525, 2025).
schizophrenia (1 paper, 2025). A major psychotic disorder characterized by abnormalities in the perception or expression of reality. "Also, ECT increases the expression of the TCF7 gene, which suppresses the function of the gene TCF7L2, which is associated with schizophrenia." (PMID 40364201, 2025).
synovial sarcoma (1 paper, 2020). "Several other genes pertaining to these networks may be dysregulated in synovial sarcoma, including LEF1, AXIN2, TCF7, and FZD homologues in the Wnt/β-catenin, HES1, and NOTCH1 in the Notch, as well as SMO and PTCH in the Sonic Hedgehog pathways." (PMID 32322158, 2020).